MB (myoglobin)
Diseases named in the same sentence as MB in open-access papers (continued):
Sharing a sentence is not in itself a finding about the gene and the disease.
pericardial effusion (2 papers, 2022 to 2024). Fluid collection within the pericardial sac, usually due to inflammation. "In the present study, we also observed that an increased serum myoglobin is linked with the presence of pericardial effusion, with a higher correlation coefficient than other cardiac markers (CK and CKMB)." (PMID 36013560, 2022). "The patients faced a 1.5-times increased risk of developing pericardial effusion for every increase in the respiratory rate with 6 breaths/minute, in platelets with 166 × 103/μL, in myoglobin with 62.5 (ng/mL), in CK, and in LDH with 166(U/L), respectively." (PMID 36013560, 2022). "We found that increased values in cardiac enzymes (myoglobin, CK, CK-MB), LDH, platelets, and CRP were associated with the presence of pericardial effusion, with myoglobin showing the highest correlation index." (PMID 36013560, 2022). "Increased values in cardiac enzymes (myoglobin, CK, CK-MB) and LDH were statistically associated with pericardial effusion." (PMID 36013560, 2022). "The occurrence of pericardial effusion presented the highest proportional correlation with myoglobin and CK." (PMID 36013560, 2022). "Patients with pericardial effusion had higher respiratory rates, coagulation parameters (D-dimers, PAI-1), leukocytes, inflammatory parameters (CRP, serum ferritin), and cardiac markers (myoglobin, CK, CK-MB, BNP, and LDH)." (PMID 36013560, 2022).
Pressure ulcers (2 papers, 2022 to 2023). "Pressure ulcers and their severity provide initial indications of a long lie duration and a possible increase in myoglobin and creatine kinase in the blood." (PMID 35840883, 2022). "This hypothesis is based on analogy to poor-healing wounds that have hemolysis and poor drainage of hemoglobin (e.g., venous stasis), and also inspired by papers showing myoglobin is detectable in distal fluids after pressure ulcers." (PMID 37267120, 2023). "First, our prior work in mathematical modeling predicted that oxidative stress from myoglobin and other DAMPs could create secondary progression of pressure ulcers." (PMID 37267120, 2023).
prostate carcinoma (2 papers, 2015 to 2023). A carcinoma that arises from epithelial cells of the prostate gland. "In contrast to muscle, MB transcription in breast and prostate cancer mainly depends on a novel, alternative promoter site." (PMID 26559958, 2015). "While investigating MB protein expression in prostate cancer, a significant positive correlation to androgen-receptor (AR) staining was observed and the analysis of publicly available transcriptome data suggested a dihydrotestosterone (DHT)-mediated suppression of the MB gene." (PMID 26559958, 2015).
sarcoma (2 papers, 1989 to 2012). A usually aggressive malignant neoplasm of the soft tissue or bone. "As expected, the Rabdhomyosarcoma markers Myogenin and Myoglobin were not expressed, further demonstrating the ability of the LMS undifferenitated cells to differentiate in vivo into a sarcoma of the same subtype as the patient tumor." (PMID 23056514, 2012).
systemic inflammatory response syndrome (2 papers, 2016 to 2024). SIRS is a serious condition related to systemic inflammation, organ dysfunction, and organ failure. "Mechanisms like rhabdomyolysis, where muscle breakdown products, particularly myoglobin, cause renal damage, and systemic inflammatory response syndrome (SIRS), which leads to widespread inflammation affecting renal perfusion, are central to this process." (PMID 39202747, 2024). "The resulting phenotypes of AKI include ischemia (reactive oxygen species/reactive nitrogen species, ROS-RNS), Systemic Inflammatory Response Syndrome (SIRS—damage-associated molecular patterns, DAMPS), sepsis (pathogen-associated molecular patterns, PAMPS), and toxicity (myoglobin)." (PMID 39202747, 2024).
thrombotic microangiopathy (2 papers, 2021 to 2023). The syndromes of microangiopathic hemolytic anemia, thrombocytopenia, and variable signs of organ impairment, due to platelet aggregation in the microcirculation. "Pathogenesis includes ischaemia, decreased renal blood flow, proteolytic degradation of the glomerular basement membrane, thrombotic microangiopathy, cytotoxic, rhabdomyolysis, and the accumulation of large amounts of myoglobin in kidney tubules." (PMID 37298463, 2023). "Besides tubular injury, thrombotic microangiopathy, widespread myoglobin casts, pauci-immune crescentic glomerulonephritis (GN), and segmental glomerulosclerosis with characteristics of healed collapsing glomerulopathy were also observed." (PMID 34057983, 2021).
thyroid (2 papers, 2015 to 2021). "Positive MB immunostaining was observed in all benign tumors (meningioma, ovarian serous papillary cystadenoma and adenomas of the thyroid and breast) and hyperplastic samples from cirrhotic liver and prostate." (PMID 33996536, 2021). "Patients with thyroid diseases can have anti-myoglobin antibodies in blood." (PMID 26675817, 2015). "Myoglobin levels have been described as being altered in cases of thyroid disease." (PMID 26675817, 2015).
anaplastic thyroid carcinoma (1 paper, 2024). "Notably, rhabdomyosarcomatous differentiation of anaplastic thyroid carcinoma is characterized by weak staining for epithelial markers and strong staining for vimentin, actin, desmin, and myoglobin." (PMID 39420880, 2024).
anterior wall myocardial infarction (1 paper, 2020). "△cTnI was divided into quartiles, and maximum △ cTnI between 4.845 and 19.073 ng/ml comprised more patients with anterior wall myocardial infarction (p < 0.001), higher GRACE score (p = 0.038), CK-MB (p = 0.023), and Myoglobin (p < 0.001)." (PMID 32774185, 2020).
Bradycardia (1 paper, 2020). A slower than normal heart rate (in adults, slower than 60 beats per minute). "These breath holding periods are associated with bradycardia, reduced skeletal muscle blood flow, and myoglobin oxygen desaturation, but this resting skeletal muscle is not under the same locomotor metabolic demands as diving." (PMID 33123026, 2020).
brain cancer (1 paper, 2021). A primary or metastatic malignant neoplasm affecting the brain. "Our data also indicate that low oxygen tensions modulate MB protein expression in different brain cancers, including GBM." (PMID 33996536, 2021). "Our data suggest that low oxygen tensions modulate MB protein expression in different brain cancers including GBM." (PMID 33996536, 2021). "We show that MB protein is expressed in a wide variety of cancers, benign tumors, cancer-adjacent normal tissues, hyperplastic tissue samples and normal brain tissue, and low oxygen tensions modulate MB protein expression in different brain cancers, including GBM." (PMID 33996536, 2021).
brain tumors (1 paper, 2021). "Hypoxia markers (CAIX and LDHA) and MB protein expression was also investigated in a TMA of different brain tumors." (PMID 33996536, 2021). "MB protein expression was positive in the majority of malignant brain tumors (60%), and CANT (90%) and normal brain tissue samples (90%)." (PMID 33996536, 2021). "MB, CAIX, and LDHA expression in tissue microarrays of normal brain tissues, brain tumors, and cancer adjacent normal tissue." (PMID 33996536, 2021). "We screened each group of TMA: multiple organ tumors (39 cases/43 cores), different brain tumors (40 cases/80 cores), and GBM tumors (40 cases/80 cores), each with its respective CANT for CAIX, LDHA, and MB protein expression." (PMID 33996536, 2021).
breast tumors (1 paper, 2015). "We therefore expect the E2-mediated suppression of MB transcription in ERα positive breast tumors to be weakened, once E2 levels start to decrease in post-menopausal females." (PMID 26559958, 2015).
bruxism (1 paper, 2013). Excessive clenching of the jaw and grinding of the teeth. "The muscle discomfort of bruxism is mainly a peripheral phenomenon, resulting from muscle hyperfunction leading to destruction of the myofibrils and release of algogenic substances including myoglobin into bloodstream." (PMID 24165294, 2013).
candidiasis (1 paper, 2025). Infection with the organism Candida. "Generally, serum anti-candidalysin IgG and IgM levels correlated with serum myoglobin and alkaline phosphatase across all candidiasis patients." (PMID 40762579, 2025).
cerebral infarction (1 paper, 2025). An ischemic condition of the brain, producing a persistent focal neurological deficit in the area of distribution of the cerebral arteries. "We confirmed that myoglobin—a biomarker highly correlated with Troponin T—also demonstrates significant utility in diagnosing cerebral infarction following aortic dissection surgery." (PMID 41366326, 2025).
cerebral malaria (1 paper, 2023). A sequestration of Plasmodium falciparum in the brain, which can cause coma and/or seizures. "Conversely, BWF associated with cerebral malaria is a pointer towards myolysis, as myoglobin has previously been detected in children with impaired consciousness and BWF." (PMID 37259110, 2023). "It is possible the source of myoglobin in the children with cerebral malaria is multifactorial." (PMID 37259110, 2023).
cervical squamous cell carcinoma (1 paper, 2021). A squamous cell carcinoma arising from the cervical epithelium. "A great deal of overlap between LDHA and MB positive samples was seen in malignant tumors apart from lung Squamous cell carcinoma, adenocarcinoma endometrium, cervical squamous cell carcinoma, osteosarcoma of the femur where LDHA immunostaining was positive while MB was negative." (PMID 33996536, 2021).
Crohn disease (1 paper, 2022). A gastrointestinal disorder characterized by chronic inflammation involving all layers of the intestinal wall, noncaseating granulomas affecting the intestinal wall and regional lymph nodes, and transmural fibrosis. "It has been shown to distinguish tissue and plasma samples from IBD and healthy controls, Crohn’s disease from ulcerative colitis, as well as active inflammation from mucosal healing based on varying profiles in lipids, phosphatidylcholines, myoglobin, and carotenoids." (PMID 35269993, 2022).
dementia (1 paper, 2023). Loss of intellectual abilities interfering with an individual's social and occupational functions. "Strikingly, there is no literature available for the association between myoglobin and CK-MB with cognitive function and dementia." (PMID 37178386, 2023).
dental caries (1 paper, 2016). The decay of a tooth, in which it becomes softened, discolored, and/or porous. "Further studies will be needed to explore the probable function of PIP and myoglobin in dental caries." (PMID 27527350, 2016). "In addition, we found prolactin inducible protein (PIP) and myoglobin might also be candidate biomarkers of dental caries." (PMID 27527350, 2016). "Meanwhile, myoglobin, one protein that was known to bind oxygen in myocardium and skeletal muscles, was not reported relevant to saliva and dental caries in previous studies." (PMID 27527350, 2016).
Duchenne muscular dystrophy (1 paper, 2012). Duchenne muscular dystrophy (DMD) is a neuromuscular disease characterized by rapidly progressive muscle weakness and wasting due to degeneration of skeletal, smooth and cardiac muscle. "Nevertheless, rhabdomyolysis with elevated myoglobin without raised CK has been reported in patients with Duchenne muscular dystrophy and malignant hypertension." (PMID 23256803, 2012).
ductal carcinoma in situ (1 paper, 2022). "The MB protein expression was upregulated in cancer cells that are challenged by prolonged hypoxia and in peri-necrotic areas of ductal carcinoma in situ (DCIS), the in vivo model of tissue experiencing hypoxia." (PMID 36223378, 2022).
embryonal sarcoma (1 paper, 2022). "UESLs are usually diffusely positive for vimentin and a1-antitrypsin and focally positive for cytokeratin, desmin, α-SMA, muscle-specific actin, CD68, myoglobin, neuron-specific enolase, S100, and CD34, suggesting that an embryonal sarcoma is undifferentiated." (PMID 36107353, 2022).
endophthalmitis (1 paper, 2025). An infectious process affecting the internal structures of the eye. "In the HVIP1 vitreous, there were a number of significant correlations identified: CRP/Myoglobin, IGFBP-4/SAA, IGFBP-4/VCAM-1, and VCAM-1/SAA in the endophthalmitis group; MPO/NGAL, CRP/SAA, and Cystatin C/Myoglobin in controls; and NGAL/MMP-9 in both groups." (PMID 40563988, 2025).
fibromyalgia (1 paper, 2021). A chronic disorder of unknown etiology characterized by pain, stiffness, and tenderness in the muscles of neck, shoulders, back, hips, arms, and legs. "Noteworthy, one of the SSc patients was classified as fibromyalgia and exhibited increased myoglobin levels." (PMID 34248959, 2021).
glioblastoma multiforme (1 paper, 2021). "MB, CAIX, and LDHA in normal brain tissues microarrays of glioblastoma multiforme, and cancer adjacent normal tissue." (PMID 33996536, 2021).
hepatitis B (1 paper, 2023). "Routine laboratory inspection items cover blood routine and blood type, urine routine, biochemical complete set, blood gas analysis, hepatitis B and other infectious disease screening, myocardial enzymes, and myocardial markers, myoglobin, coagulation five items inspection." (PMID 37426822, 2023).
hypercoagulable (1 paper, 2015). "Increased blood viscosity caused by colloids or myoglobin release, RBC transfusion and hypercoagulable states are among the factors determining microcirculatory blood flow through the PBP." (PMID 25886728, 2015).
hyperlipidaemia (1 paper, 2025). "In the present study, we screened the best predictor variables (DBP, Killip class, hyperlipidaemia, GRACE Score, CKMB, myoglobin, WBC, monocytes, TT, GLB, and CB) using LASSO regression." (PMID 40757200, 2025). "We used 11 variables selected by LASSO regression (DBP, Killip class, hyperlipidaemia, GRACE Score, CKMB, myoglobin, WBC, monocytes, TT, GLB, and CB) to construct two survival models (coxph and rfsrc) to predict the survival and prognosis of STEMI patients." (PMID 40757200, 2025). "According to Patient #204’s SurvSHAP(t) plot, the absence of hyperlipidaemia increased the patient’s chances of survival in the coxph model, whereas myoglobin increased the patient’s chances of survival in the rfsrc model." (PMID 40757200, 2025).
influenza infection (1 paper, 2023). "Another study demonstrated 21 patients who died of influenza infection all exhibited mild to moderate severity of ATN and four patients had myoglobin pigment deposited in the renal tubules." (PMID 37376487, 2023).
interstitial lung disease (1 paper, 2023). A diverse group of lung diseases that affect the lung parenchyma. "Roseburia was negatively correlated with myoglobin (MYO), cardiac troponin T (cTnT), ESR, CRP, and the occurrence of interstitial lung disease (ILD)." (PMID 37692165, 2023).
ischemic stroke (1 paper, 2025). A stroke disorder caused by obstruction of blood flow to the brain, due to thrombotic (local blood clot formation) or embolic (due to a blood clot or other material traveling from another site) event. "We identified intraoperative blood loss, intraoperative plasma transfusion, and myoglobin levels as risk factors for postoperative ischemic stroke." (PMID 41366326, 2025).
Jaundice (1 paper, 2014). Yellow pigmentation of the skin due to bilirubin, which in turn is the result of increased bilirubin concentration in the bloodstream. "Presence of jaundice and different pigments such as myoglobin and hemoglobin inside the kidney tubules and bile ducts indicated that red blood cells and muscle cells had been destroyed by melittin and phospholipase A2." (PMID 25584045, 2014).
liver cancer (1 paper, 2021). An epithelial or non-epithelial malignant neoplasm that arises from the liver. "Recently, a number of disease-biomarker aptamers were successfully selected by microfluidic technology, such as platelet derived growth factor BB (PDGF-BB) protein for various pathological states, myoglobin for cardiovascular disease, and alpha-fetoprotein for liver cancers." (PMID 34604229, 2021).
lung adenocarcinoma (1 paper, 2021). A carcinoma that arises from the lung and is characterized by the presence of malignant glandular epithelial cells. "In that respect, it is interesting that in patients with lung adenocarcinoma, high MB levels were linked to a poorer patient prognosis, indicating cancer-specific differences of MB function." (PMID 34671319, 2021).
mesenchymal tumor (1 paper, 2016). "A diagnosis of malignant mesenchymal tumor was excluded due to negativity for desmin, smooth muscle actin, caldesmon, CD34, CD10, and myoglobin." (PMID 27491291, 2016).
minimal change nephropathy (1 paper, 2026). "Subsequent dark brown urine and hematuria were likely caused by increased myoglobin levels and dysferlin deficiency in podocytes, which may be associated with minimal change nephropathy." (PMID 41517735, 2026).
Mitochondrial myopathy (1 paper, 2022). "Increased myoglobin levels in circulation is a known feature of mitochondrial myopathy." (PMID 35267991, 2022).
myocardial disease (1 paper, 2024). "Ultrasensitive troponin, myoglobin and CK-MB are well validated biomarkers of myocardial disease, regardless of the type of MI, but sometimes not helpful in this context." (PMID 38792487, 2024).
necrosis (1 paper, 2024). The phenotypic observation that death has occurred in groups of cells or in one or more tissues due to external factors, such as infection, toxins, mechanical trauma, loss of blood supply and other injuries (e.g. corrosion or burning). "It is often accompanied by acute tubular necrosis, secondary to hemodynamic disturbances and precipitation of hemoglobin or myoglobin in the renal tubules." (PMID 39171036, 2024).
Pancytopenia (1 paper, 2013). An abnormal reduction in numbers of all blood cell types (red blood cells, white blood cells, and platelets). "Upon admission to our ward the patient showed grade (G) 4 pancytopenia and a marked increase in liver lytic enzymes, serum levels of myoglobin, creatine phosphokinase (CPK) and lactate dehydrogenase." (PMID 23899130, 2013).
paragonimiasis (1 paper, 2021). A parasitic infection caused by trematodes of the Paragonimus genus. "Two recombinant proteins (a cysteine protease and a myoglobin) showed the highest sensitivity and specificity as diagnostic antigens, and they detected antibodies in sera from paragonimiasis patients with early or mature infections." (PMID 33415393, 2021).
PEComas (1 paper, 2012). "Nevertheless, PEComas should have smooth muscle differentiation such as SMA reactivity rather than striated muscle differentiation such as myoglobin reactivity." (PMID 22973317, 2012).
Premature atrial contractions (1 paper, 2021). A type of cardiac arrhythmia with premature atrial contractions or beats caused by signals originating from ectopic atrial sites. "Premature atrial contractions (PAC) and nonsustained atrial tachycardia (NSAT) were significantly positively correlated with plasma CKMB levels but not with high-sensitive cardiac troponin I or myoglobin levels." (PMID 33777449, 2021).
pulmonary aspergillosis (1 paper, 2025). "An 82-year-old woman with pulmonary aspergillosis developed dark-colored urine, markedly elevated creatine kinase (3,125 U/L) and myoglobin (3884.4 ng/mL), and delayed myocardial injury (high-sensitivity troponin I: 26301.6 pg/mL) on day 2 after intravenous micafungin (200 mg/day) initiation." (PMID 41426586, 2025).
pulmonary diseases (1 paper, 2025). "Studies have shown that an increased level of myoglobin may be caused by other pre-existing illnesses, like liver or pulmonary diseases or cancer." (PMID 40149648, 2025).
pulmonary hypertension (1 paper, 2016). Increased pressure within the pulmonary circulation due to lung or heart disorder. "A decrease in myoglobin (Mb) concentration has also been reported in rat models of pulmonary hypertension (PH) with progressive heart failure (HF) but not with stable HF." (PMID 27572699, 2016).